SOX4 (SRY-box transcription factor 4)
Diseases named in the same sentence as SOX4 in open-access papers (continued):
Sharing a sentence is not in itself a finding about the gene and the disease.
hepatoblastoma (3 papers, 2023 to 2025). Hepatoblastoma (HB) is a malignant hepatic tumor and is the most common pediatric liver cancer. "A cholangiocyte-like subpopulation expresses FGF19, in a SOX4-dependent, paracrine manner, to drive the proliferation of neighboring embryonal hepatoblastoma cells." (PMID 40684183, 2025). "Finally, we determined whether FGF19 expression in HB15 and HB17 depends on the biliary transcriptional program, as FGF19 expression was found in a subset of the SOX4-expressing embryonal hepatoblastoma cells with cholangiocytic features." (PMID 39567523, 2024). "FGF19-producing cholangiocytic-like hepatoblastoma cells are characterized by high WNT/b-catenin signaling, a low proliferation rate, and expression of cholangiocyte markers KRT19 and SOX4, a transcription factor important in biliary-lineage differentiation." (PMID 40684183, 2025). "As a control, spatial transcriptomic analyses of a section of normal liver from a patient with hepatoblastoma showed very low expression of FGF19, AXIN2, and SOX4, without apparent co-localization." (PMID 39567523, 2024).
Insulin resistance (3 papers, 2022 to 2025). Increased resistance towards insulin, that is, diminished effectiveness of insulin in reducing blood glucose levels. "In addition, SOX4 AKO mice developed more severe insulin resistance and glucose intolerance with HFD." (PMID 36451857, 2022). "Furthermore, HFD-fed Sox4-MKO mice displayed more severe glucose intolerance and insulin resistance than their control counterparts." (PMID 39402212, 2025).
microcephaly (3 papers, 2015 to 2024). A congenital or acquired developmental disorder in which the circumference of the head is smaller than normal for the person's age and sex. "As in other SOX gene-associated brain size defects, the microcephaly phenotype observed in individuals with SOX4 or SOX11 variants has low penetrance, suggesting a complex interplay between SOX genes and other unidentified genes that variably affect the consequences of the SOX gene deficiency." (PMID 38094004, 2023). "In this study, I will focus on two members of the SOXB1 group (SOX2 and SOX3) and two members of the SOXC group (SOX4 and SOX11) for their associations with microcephaly." (PMID 38094004, 2023). "Mice engineered to be conditionally mutant for both Sox4 and Sox11 die at birth with microcephaly and an ear phenotype." (PMID 38094004, 2023).
prostate adenocarcinoma (3 papers, 2024). "Diagnostic accuracy of P4HB and SOX4 in prediction of prostatic adenocarcinoma." (PMID 39118797, 2024). "Relation of H Score of P4HB and SOX4 to clinicopathological parameters in the studied participants with prostatic adenocarcinoma." (PMID 39118797, 2024). "Relation between the status of ERG and H score and IRS of both P4HB and SOX4 in the studied participants with prostatic adenocarcinoma." (PMID 39118797, 2024). "Chromatin immunoprecipitation assays have confirmed the binding of estrogen receptor B to the SOX4 gene promoter in prostate adenocarcinoma cells (LNCaP), suggesting a regulation of SOX4 through estrogen signaling, a prominent process in controlling the timing of labor onset in the myometrium." (PMID 38635533, 2024).
rectal cancer (3 papers, 2012 to 2022). A primary or metastatic malignant neoplasm that affects the rectum. "Lately, MicroRNA-130a (miR-130a) has been spectacularly upregulated in radiosensitive rectal cancer cells where overexpression of miR-130a promotes rectal cancer cell radiosensitivity by targeting SOX4." (PMID 35626648, 2022). "Copy number increase of EFNA1 (1q22), PTGS2 (1q31.1), KDM5B (1q32.1), ESRRG (1q41), KIFC1 (6p21.32), PBX2 (6p21.32) and SOX4 (6p22.3) were only detected in rectal cancer in array CGH." (PMID 23158542, 2012).
retinoblastoma (3 papers, 2016 to 2024). A malignant tumor that originates in the nuclear layer of the retina. "Single-cell transcriptomic characterization of intraocular and extraocular retinoblastoma suggests that SOX4 may drive the local extension of retinoblastoma." (PMID 38172218, 2024). "Besides the well-established driver genes RB1 (13q-loss) and MYCN (2p-gain) we identified CRB1 and NEK7 (1q-gain), SOX4 (6p-gain) and NUP205 (7q-gain) as novel retinoblastoma driver candidates." (PMID 27115612, 2016).
sarcoma (3 papers, 2021 to 2026). A usually aggressive malignant neoplasm of the soft tissue or bone. "In addition, the relative mRNA expression of SOX4 in breast, liver, ovarian, pancreatic, and thyroid cancer as well as sarcoma datasets in the Oncomine database, was visualized." (PMID 34442467, 2021). "Increased expression of SOX7 and SOX9, as well as cooperation between SOX7 and SOX4, are involved in the process in which upregulation of slug by SOX4, β-catenin/p300 complexes induces EMT and related CSC properties, which in turn promote homologous and heterologous sarcoma components in UCS." (PMID 34881182, 2021).
T-cell acute lymphoblastic leukemia (3 papers, 2018 to 2022). Acute lymphoblastic leukemia of T-cell origin. "In summarization, we concluded that circular RNA circPRKCI contributed to malignant progression of T-cell acute lymphoblastic leukemia by modulating miR-20a-5p/SOX4 axis." (PMID 34695805, 2021). "To summarize, we concluded that circular RNA circPRKCI contributed to malignant progression of T-cell acute lymphoblastic leukemia by modulating miR-20a-5p/SOX4 axis." (PMID 34695805, 2021). "Interestingly, it has recently been found in T-cell acute lymphoblastic leukaemia, a haematological disease, that miR-204 binds to SOX4 to inhibit proliferation, migration and invasion." (PMID 29382303, 2018).
T-cell leukemia (3 papers, 2021 to 2024). A malignant disease of the T-lymphocytes in the bone marrow, thymus, and/or blood. "SOX4 is considered as one of the oncogene which is often found in cancers, it was observed that SOX4 was involved in the process of T cell leukemia and SOX4 could regulate the expression of CXCL13 in human T helper cells." (PMID 35577802, 2022).
acute myocardial infarction (2 papers, 2024 to 2025). Necrosis of the myocardium, as a result of interruption of the blood supply to the area. "Furthermore, silencing Sox4 diminished the area of cardiac infarction, improved heart function, and reversed Sox4-induced cardiomyocyte apoptosis in mice with myocardial infarction." (PMID 39518344, 2024).
acute pancreatitis (2 papers, 2022 to 2024). An acute inflammatory process that leads to necrosis of the pancreatic parenchyma. "SOX4 functioned in promoting cell proliferation, pancreatic development and epithelial-mesenchymal transition, which has not been reported in acute pancreatitis." (PMID 38605381, 2024).
adenoma (2 papers, 2018 to 2020). A neoplasm arising from the epithelium. "In line with the effect of Ap4 deletion in adenomas, GSEA indicated that mRNAs characteristic for Lgr5-positive ISCs and several factors involved in Wnt/β-catenin and Notch signaling pathways were preferentially downregulated upon deletion of Ap4: for example Sox4, Axin2, EphB3 were downregulated." (PMID 30177706, 2018).
astrocytoma (2 papers, 2013 to 2021). "This pattern was maintained in secondary GBM and further confirmed by immunohistochemistry, suggesting a role for ID4, SOX2 and SOX4 in early astrocytoma tumorigenesis." (PMID 23613880, 2013). "On the contrary, ASCL1 and SOX4 expression were clearly more expressed in OLIG1+ cells in both the explored oligodendroglioma and astrocytoma samples." (PMID 33925547, 2021). "Positive correlation was found when comparing ID4 relative expression of infiltrative astrocytomas with SOX2 (r = 0.50; p<0.005), SOX4 (r = 0.43; p<0.005) and OCT-4 (r = 0.39; p<0.05)." (PMID 23613880, 2013).
atherosclerosis (2 papers, 2025). A disease characterized by the build-up of fatty material and calcium deposition in the arterial wall resulting in partial or complete occlusion of the arterial lumen. "Unsupervised DEGs analysis of SMCs revealed increased expression in Abcb8ECKO of TGF-β-pathway genes such as Tgfb1, Tgfb2, Tgfb3, Mmp2 and Col1a1, inflammatory genes such as Ccl2 (encoding for MCP1) and Csf1 as well as atherosclerosis-associated genes including Egr1, Sqstm1, Irf1, Sox4 and Xylt1." (PMID 41252867, 2025).
atrial fibrillation (2 papers, 2024 to 2025). A disorder characterized by an electrocardiographic finding of a supraventricular arrhythmia characterized by the replacement of consistent P waves by rapid oscillations or fibrillatory waves that vary in size, shape and timing and are accompanied by an irregular ventricular response. "Recently, atrial fibrillation was reported to be a major clinical manifestation of CSS caused by a novel SOX4 mutation." (PMID 40426787, 2025).
cervical squamous cell carcinoma (2 papers, 2021 to 2023). A squamous cell carcinoma arising from the cervical epithelium. "In cervical squamous cell carcinoma, FAT1 positively correlated with SOX4, and upregulated it to promote migration and invasion of cancer cells." (PMID 34580376, 2021).
chronic lymphocytic leukemia (2 papers, 2022 to 2025). "SRY-box transcription factor 4 (SOX4) is a transcription factor involved in early B cell development and has been implicated in various malignancies; however, its role in chronic lymphocytic leukemia (CLL) remains poorly understood." (PMID 40613823, 2025). "However, SOX4 is also upregulated in ductal carcinoma in situ and invasive breast carcinoma but downregulated in two sets of chronic lymphocytic leukemia." (PMID 36101460, 2022).
Cirrhosis (2 papers, 2021 to 2024). A chronic disorder of the liver in which liver tissue becomes scarred and is partially replaced by regenerative nodules and fibrotic tissue resulting in loss of liver function. "The following clinical features were used to construct a nomogram for RFS: BCLC stage, cirrhosis, gender and SOX4 expression." (PMID 33995626, 2021). "Considering that COL1A2 is a collagen, we performed a correlation analysis between SOX4, LGALS3, SERPINE2, CD52, LPXN, and MPP6 and the progression of cirrhosis." (PMID 39194690, 2024). "Next, we constructed a nomogram for OS based on the following clinical features: BCLC stage, cirrhosis, serum AFP level, tumor size and SOX4 expression." (PMID 33995626, 2021).
coloboma (2 papers, 2014 to 2023). An abnormality in which a part of a structure in one or both eyes is missing. "We then injected sox4 mRNA into sox11 morphants and found that this significantly reduced the proportion of embryos with lens and coloboma phenotypes." (PMID 25010521, 2014). "Consistent with this hypothesis, we observed a significantly greater proportion of embryos with coloboma in sox4/sox11 double morphants than when either gene was knocked down alone (data not shown)." (PMID 25010521, 2014).
diabetic retinopathy (2 papers, 2024). "Additionally, SOX4 was found to promote angiogenesis and inflammation in HG‐stimulated retinal endothelial cells, which might serve as a promising target for diabetic retinopathy." (PMID 38751373, 2024).
gastric tumor (2 papers, 2012 to 2021). "For example, in gastric tumor cells, the circ-DONSON recruits the SMARCA1-NURF complex to the SOX4 promoter by directly interacting with SMARCA1, which facilitates tumor cell development via enrichment of the active markers H3K27ac and H3K4me3 on the promoter and activation of SOX4 transcription." (PMID 34736517, 2021).
head and neck squamous cell carcinoma (2 papers, 2015 to 2025). A squamous cell carcinoma that arises from any of the following anatomic sites: lip and oral cavity, nasal cavity, paranasal sinuses, pharynx, larynx, and salivary glands. "In the present study, we investigated whether SOX4 affects tumor cell behaviors such as cell proliferation, apoptosis, invasion, migration, and chemoradiation-induced apoptosis in head and neck squamous cell carcinoma (HNSCC) cells to validate its potential as a novel molecular target." (PMID 26555193, 2015).
Hepatic steatosis (2 papers, 2024). Steatosis is a term used to denote lipid accumulation within hepatocytes. "SOX4 in the liver binds to the proximal promoter region of SREBP-1c and upregulates SREBP-1c expression, promoting hepatic steatosis." (PMID 39194690, 2024).
liver disease (2 papers, 2015 to 2024). "Thus, we reveal a novel mechanism underlying Sox4 expression and HBV replication, identify a new role of Sox4 in regulating viral replication, and provide new insights into the mechanism underlying chronic HBV infection that leads to the development of liver diseases." (PMID 25970172, 2015).
mantle cell lymphoma (2 papers, 2010 to 2021). Mantle cell lymphoma is a rare form of malignant non-Hodgkin lymphoma affecting B lymphocytes in the lymph nodes in a region called the ``mantle zone''. "In this study we found variable expression of SOX11, SOX4 and SOX12 mRNA in mantle cell lymphoma cell lines." (PMID 21124928, 2010).
metastatic tumor (2 papers, 2018 to 2019). "Additionally, the expression of SOX4 was increased in LINC01133 knockdown lung metastatic tumours, while the expression of LINC01133 was decreased in LINC01133 knockdown lung metastatic tumours." (PMID 31557401, 2019).
myopia (2 papers, 2024 to 2025). "It was found that high myopic associated proteins (ASXL1 FGFR3 ERBB3 SOX4) can affect ARID1B protein by affecting ARIDIA protein, and COL2A1 protein can also affect ARIDIA protein by affecting FGFR3 protein, resulting in the clinical phenotype of patients with high myopia." (PMID 38790056, 2024). "Therefore, we propose that SOX11 may directly or indirectly affect proteins with strong links to high myopia, such as COL9A1, COL2A1, and COL11A1, by affecting the expression or function of SOX4, ultimately causing the clinical phenotype of eoHM and dystrophy of cone-rod cells in CSS9 individuals." (PMID 40933692, 2025). "Analysis of protein interactions in the STRING online database revealed that the ARID1A protein interacts with the high myopia gene-related proteins FGFR3, ASXL1, ERBB3, and SOX4, whereas the ARID1A protein antagonizes the ARID1B protein." (PMID 38790056, 2024).
Nephroblastoma (2 papers, 2024). An embryonal neoplasm characterized by the presence of epithelial, mesenchymal, and blastema components. "Furthermore, the patient carrying the smallest deletion (389 kb, SOX4 only) had nephroblastoma, with a paradoxical increased tumour/normal kidney SOX4 expression ratio." (PMID 38397148, 2024).
oral lichen planus (2 papers, 2022). Oral lichen planus is a chronic inflammatory oral condition of unknown aetiology characterized by T-cell-mediated chronic immune response and abnormal epithelial keratinization cycle. "Moreover, our previous research also revealed that Sox4 is significantly upregulated in oral lichen planus (OLP), OSCC versus OLP tissues, and Sox4 might be actively involved in the progression of OLP to OSCC, suggesting that Sox4 could induce the progression in OLP-associated OSCC." (PMID 35513871, 2022).
papillary thyroid carcinoma (2 papers, 2025 to 2026). "Targeting CCND1 and its OS-mediated regulatory pathways offers a promising therapeutic strategy for PTC.CCND1, oxidative stress, papillary thyroid carcinoma, single-cell RNA sequencing, SOX4, TFF3." (PMID 41646983, 2026).
speech delay (2 papers, 2024). "In OMIM (#618506), SOX4-related disorder is now classified as “intellectual developmental disorder with speech delay and dysmorphic facies” (CSS10 being listed as alternative title)." (PMID 38397148, 2024).
squamous cell carcinoma (2 papers, 2020 to 2025). A carcinoma arising from squamous epithelial cells. "In squamous cell carcinoma, KLF5 positively regulates Sox4 expression, and KLF5/Sox4 regulatory signaling facilitates tumorigenesis." (PMID 41465103, 2025).
thyroid cancer (2 papers, 2021 to 2023). "We validated the downregulation of SNAI2, SOX4, and TGFBR2, three targets never investigated in thyroid cancer cells, and of HMGA2, a miR-2 04-5p target previously identified in the lab (unpublished results), in TPC-1 and BCPAP cells following miR-204-5p overexpression." (PMID 37445942, 2023).
type 2 diabetes (2 papers, 2020 to 2022). "Separately, although the regulatory elements implicating SOX4 –a gene involved in insulin secretion–overlapped with a different gene (CDKAL1), this distal locus has indeed previously been studied and found to incriminate SOX4 in the context of type-2 diabetes." (PMID 35316269, 2022).
uterine carcinosarcoma (2 papers, 2016 to 2024). A usually aggressive malignant neoplasm arising from the uterine corpus and less often the cervix. "Knocking down SOX4 has been shown to attenuate AKT and β-catenin activities, leading to a decrease in the invasive characteristics of uterine carcinosarcoma." (PMID 39349443, 2024).
viral infection (2 papers, 2015 to 2021). "Here, we discover novel roles of miR-335, miR-129-2, and miR-203 in HBV-regulated Sox4 expression, and identify an association between viral infection and miR-335, miR-129-2, and miR-203 expression." (PMID 25970172, 2015). "Taken together, we demonstrated that virus infection activates Sox4, which in turn facilitates viral replications." (PMID 33517839, 2021). "We demonstrate that YY1 is required for up-regulating Sox4 expression mediated by HBV and thus, reveal a new role of YY1 in activating Sox4 expression and an association between YY1 expression and viral infection." (PMID 25970172, 2015). "The correlation between viral infection and Sox4 function was initially evaluated." (PMID 33517839, 2021). "The expression of sex-determining region Y-box 4 (Sox4) is induced by virus infection in viral infected patients and cultured cells, which subsequently represses the TLR signaling network to facilitate viral replication at multiple levels by a distinct mechanism." (PMID 33517839, 2021). "As Sox4 is a transcriptional factor, we want to evaluate if the activated Sox4 by viral infection could in turn have functions in the regulation of viral replication." (PMID 33517839, 2021). "Here, we demonstrate that Sox4 expression is elevated in HBV-associated HCC tissues and HBV-transfected cells and that Sox4 expression is tightly controlled by HBV, which provides the first evidence suggesting a correlation between Sox4 expression and viral infection." (PMID 25970172, 2015). "The levels of p-IRAK4, p-TAK1, and p-TBK1 were activated by SeV, but repressed by Sox4, indicating that Sox4 attenuates both TLR/MyD88/IRAK4/TAK1 and TLR/TRIF/TRAF3/TBK1 pathways in response to viral infections." (PMID 33517839, 2021). "Taken together, Sox4 facilitates the degradation of NF-kB and IRF3/7, which leads to the repression of IFNs during viral infection." (PMID 33517839, 2021). "But, the role of Sox4 in viral infection and pathogenesis has not been elucidated." (PMID 25970172, 2015). "However, the role of Sox4 in viral infection has not been reported." (PMID 25970172, 2015).
acral melanoma (1 paper, 2025). "Particularly in acral melanoma (AM), little were known for SOX6 in promoting AM progression, compared to other SOX family members like SOX4 and SOX10." (PMID 40866912, 2025).